INS (insulin)
Diseases named in the same sentence as INS in open-access papers (continued):
Sharing a sentence is not in itself a finding about the gene and the disease.
Insulin resistance (continued). "Peripubertal DHT-induced PCOS female rats and mice exhibit elevated fasting blood glucose levels, decreased glucose tolerance, and development of insulin resistance at adult age as measured by euglycemic hyperinsulinemic clamp, oral glucose tolerance test, and insulin tolerance test." (PMID 32310267, 2020). "Notably, across the spectrum from obesity to T2D, insulin resistance appears to be a common feature, and as such, insulin-producing islet β cells are considered central determinants in the transition from normoglycemia to dysglycemia." (PMID 33353164, 2020). "The higher FKBP51 expression was associated with reduced insulin effects on glucose uptake, suggesting that FKBP51 may be implicated in GC-induced insulin resistance." (PMID 33066464, 2020). "Due to time andfinancial constraints, we did not perform a hyperinsulinaemic euglycaemic clamp, the ‘goldstandard’ for the measurement of insulin sensitivity but we did see that dapagliflozinresulted in a significant reduction in HOMA-IR an index for insulin resistance." (PMID 32578850, 2020). "GK rats exhibit impaired glucose metabolism and insulin secretion and insulin resistance." (PMID 32566684, 2020). "Much evidence has suggested that overactivation of the IR/insulin axis, present in different metabolic disorders characterized by insulin resistance and hyperinsulinemia, plays a putative role in TC tumorigenesis being associated with TC increased risk and worse prognosis." (PMID 33114365, 2020). "Type 2 diabetes is a multifactorial disease with insulin secretion failure and insulin resistance." (PMID 32097444, 2020). "Moreover, pubertal children with prediabetes HbA1c levels had the higher AUC of glucose and insulin, degree of insulin resistance, and proportion of patients with AGT than pubertal children with normal HbA1c." (PMID 33224197, 2020). "Furthermore, clinical studies are needed to determine the importance of insulin regulation of endometrial function and decidualization in patient groups with insulin resistance and hyperinsulinemia." (PMID 33218355, 2020). "Another research group seeking to determine whether insulin-sensitizing drugs improve secretion of GLP-1 studied catch-up growth rats that display insulin resistance and impaired incretin effect after pioglitazone treatment." (PMID 32656265, 2020). "Interestingly, daily treatment with fructose was also found to tend to attenuate fasting insulin (p = 0.058) and to reduce insulin resistance as compared to an equivalent amount of sucrose." (PMID 32751772, 2020). "In addition, endocrine resistance (p = 1.85E−15), insulin signaling pathway (p = 1.04E−06), insulin resistance (p = 1.91E−04), type II diabetes (p = 5.23E−04), and other signaling pathways also involved." (PMID 33134394, 2020). "In addition, the same study showed that estrogen contributes to insulin sensitivity in females, and testosterone exacerbates insulin resistance in C57BL/6 J mice." (PMID 33143653, 2020). "The issues related to insulin resistance could be minimized through alternative non-insulin dependent GLUT1 pathway." (PMID 32703184, 2020). "It was Gerald Reaven who first named this cluster of risk factors “insulin resistance syndrome” (IRS) after discovering an inverse relationship between MetS and insulin sensitivity, as insulin resistance seems to be the main determinant in the development of this syndrome." (PMID 32752277, 2020). "Insulin resistance is characterized by a defective response (“resistance”) to normal insulin concentrations to uptake the glucose present in the blood, and is the underlying condition that leads to type 2 diabetes (T2D) and increases the risk of cardiovascular disease." (PMID 33362275, 2020). "As such, the true clinical relevance of this novel, insulin-independent pathway to improve whole-body glucose homeostasis (namely, three conditions: glucose tolerance, insulin resistance and hepatic steatosis) could be readily tested in humans." (PMID 32472192, 2020).
Insulin resistance (continued). "However, among obese people, individuals with high insulin resistance had a lower amount of H6P compared to insulin-sensitive adults." (PMID 32245262, 2020). "The insulin sensitivity in our model could be an adaptation to insulin resistance by increasing insulin secretion." (PMID 33013934, 2020). "This selective model of insulin resistance might be induced by different nutritional stimulators and a combination of nutritional and hormonal model that includes multiple modes of insulin signalling pathways regulations is proposed." (PMID 32670384, 2020). "The major metabolic defect of T2DM are; 1) insulin resistance where the sensitivity of insulin action in liver, muscle, and adipose tissue is impaired and 2) reduced ability of the pancreatic beta cells to produce enough insulin to compensate for insulin sensitivity loss." (PMID 32694996, 2020). "Furthermore, zinc and magnesium have direct and indirect effects on the secretion and signal transduction of insulin and in the development of insulin resistance." (PMID 32098371, 2020). "Furthermore, peripheral insulin resistance can directly contribute to brain insulin resistance by compromising transport of insulin into the central nervous system." (PMID 32697764, 2020). "A validated adipose tissue-insulin resistance (IRi) index (Adipo-IRi = plasma-free fatty acids (NEFA) x fasting plasma insulin [FPI] [mmol/L/pmol/L]) is calculated based on the linear relationship between the rise in the FPI level and inhibition of the rate of fasting plasma NEFA." (PMID 32272872, 2020). "No significant improvements were observed in the clinical parameters of group C. Fasting insulin (Δ − 5.9, and Δ − 5.7) and homeostatic model assessment of insulin resistance (HOMA-IR) (Δ − 1.1 and Δ − 0.5) were decreased in both RO and AO groups, respectively." (PMID 32563253, 2020). "The inhibition of Akt, a key mediator of cellular insulin sensitivity, may stimulate gluconeogenesis and hepatic insulin resistance." (PMID 32807188, 2020). "At baseline and post-intervention, anthropometrics, body composition, systemic inflammation (high-sensitivity C-reactive protein, tumor necrosis factor-α, and interleukin 6), fasting glucose, insulin and homeostasis model assessment-insulin resistance (HOMA-IR) were determined." (PMID 33126555, 2020). "It is unclear whether healthy overweight or obese individuals can maintain insulin sensitivity during their entire life or whether these statuses simply represent the delayed onset of obesity-related insulin resistance." (PMID 32879953, 2020). "Insulin resistance and impaired insulin secretion are two main characteristics of type 2 diabetes." (PMID 32013797, 2020). "We can conclude that adenosine receptors exert opposite actions in modulating insulin action in control and insulin resistant animals, with A2 chronic adenosine receptors antagonists promoting insulin resistance in control animals and rescuing this phenotype in insulin-resistance states." (PMID 32411098, 2020). "However, the combination of insulin’s instability and the c-peptide’s longer half-life has led to significant interest in using c-peptide as a proxy for insulin in measures of insulin resistance." (PMID 32375229, 2020). "Furthermore, the previous studies reported that the reduction of body weight in type 2 diabetes is associated with a fall in fasting blood glucose, a reduction in serum insulin concentrations and improved insulin resistance." (PMID 32922365, 2020). "Cellularly, BP 2.9 could increase the activity of insulin and could ameliorate palmitic acid-induced insulin resistance in C2C12 myotubes." (PMID 32759739, 2020). "This study identified a novel role for miR-27 in regulating insulin signaling, and this finding suggests that elevated miR-27 levels may contribute to early development of hepatic insulin resistance." (PMID 33212990, 2020).
Insulin resistance (continued). "Catechins could effectively reduce the ovarian and uterine organ coefficients, reduce the levels of E2, FSH and LH in the blood and the ratio of LH/FSH, and improve glucose metabolism and insulin resistance in PCOS mice induced by insulin combined with hCG." (PMID 33292347, 2020). "Insulin resistance is a pathological condition in which cells fail to respond to insulin normally." (PMID 32158492, 2020). "Experimental studies showed that insulin resistance could lead to compensatory hyperinsulinemia, which enhanced the cross-binding of insulin to the insulin-like growth factor-1 (IGF-1) receptors expressed on breast epithelial cells." (PMID 32015762, 2020). "Coptis can improve insulin action on target cells and relieve insulin resistance." (PMID 32846751, 2020). "Perhaps most importantly, cadherin-13 (also known as T-cadherin) has been demonstrated to be a regulatory component of insulin signaling endothelial cells, and may in fact be a determinant of the development of endothelial insulin resistance." (PMID 32596266, 2020). "The mechanisms underpinning the association between high FIB-4 index and a decreased insulin secretion are uncertain if insulin resistance is not the key mediator." (PMID 32978491, 2020). "Conversely, delivery of Mafg alone caused insulin resistance, but not when coupled to LincIRS2 loss, suggesting independent roles in regulating insulin sensitivity." (PMID 32005828, 2020). "In order to further analyze the gut microbiome mediated insulin resistance by inducing inflammation, we also analyzed the correlation between inflammatory factors and gut microbiome, as well as the correlation between inflammatory factors and fasting insulin." (PMID 32973686, 2020). "Moreover, previous studies suggested that exposure to air pollution induces oxidative stress and adipose tissue inflammation, which disrupts insulin signaling and results in insulin resistance." (PMID 33298083, 2020). "Higher leptin levels were found in macrosomic newborns and are related to insulin levels and adiposity; this may explain how fetuses of obese mothers develop insulin-resistance in the womb and are born with higher adiposity." (PMID 33424775, 2020). "For example, saccharin, an artificial sweetener, could potentiate glucose-stimulated insulin release from isolated pancreatic β-cells, leading to insulin resistance and potentially weight gain." (PMID 32853224, 2020). "It is worth mentioning here that dietary FAs are capable of modulating the deleterious effects of insulin resistance by alterations to the functionalities of membrane proteins involved in insulin activity—among others, CD36—and their effects on the metabolism of glucose and FAs." (PMID 32796572, 2020). "TNF-α is involved in glucose and insulin metabolism, lipolysis, and insulin resistance." (PMID 32188105, 2020). "Unlike T2D which is caused by insulin resistance, T1D is an autoimmune disorder resulting in the destruction of the pancreatic ß-cells that secrete insulin." (PMID 31929591, 2020). "However, increased insulin demands, as known from prediabetes or insulin resistance, lead to an occurrence of α‐cells inside the core." (PMID 32374082, 2020). "Insulin resistance is characterized by an over secretion of insulin resulting in hyperinsulinemia that induces triglyceride accumulation and lipolysis inhibition in tissues via glucose transporter-4 (GLUT4), mediated by the phosphatidylinositol 3-kinase (PI3K) signaling pathway." (PMID 32326415, 2020). "Researchers thought that hypokalemia may decrease insulin secretion and induce insulin resistance, followed by dysbiosis of glucose metabolism." (PMID 32117054, 2020). "Serum collected from fasted individuals showed a modest inverse correlation between serum BCFA concentrations and an index of insulin resistance (homeostatic model of assessment of insulin resistance), suggesting that BCFAs may promote insulin sensitivity." (PMID 32962219, 2020).
Insulin resistance (continued). "Significant loci were also related to body mass index (BMI), systolic blood pressure (SBP), serum high-density lipoprotein cholesterol (HDL-C), triglyceride (TG), and fasting blood glucose (FBG), adipokines, and insulin as well as insulin resistance (p < 0.05)." (PMID 32887252, 2020). "Interestingly, people with insulin resistance have been noted to have normal fasting vascular function, but impaired conduit or microvascular insulin action." (PMID 32849302, 2020). "All together, the relation of HDL size and large HDL particles with incident PTDM in RTRs could conceivably be explained, at least in part, by increased insulin resistance or impaired insulin secretion." (PMID 32245262, 2020). "This review discusses the main role of mitochondria in the development of insulin resistance, which leads to pathological processes in insulin-dependent tissues, and considers potential therapeutic directions based on the modulation of mitochondrial biogenesis." (PMID 32904391, 2020). "Corticosteroids harm insulin signaling and functioning, resulting in insulin resistance." (PMID 33036127, 2020). "Higher percentage methylation of the two FKBP5 CpG sites correlated with adiposity (body mass index and waist circumference), insulin resistance (homeostasis model for insulin resistance, fasting insulin and plasma adipokines) and systemic inflammation (c-reactive protein) in both adipose depots." (PMID 32958048, 2020). "Together, these results suggest that miR-378b controls insulin sensitivity by targeting the insulin receptor (IR) as well as p110α and possibly play an inhibitory role in the development of insulin resistance, thereby providing insights into the development of novel diagnostic and treatment methods." (PMID 32508647, 2020). "In agreement to that, phenolic compounds derived from coffee silverskin extract, including CA and CGA, prevented insulin resistance and improved lipid metabolism in murine adipocytes model via the insulin/PI3K/AKT pathway and elevated PGC-1α and UCP1 protein expression levels." (PMID 33371201, 2020). "This suggests that anti-inflammatory aspects of insulin activity may be unchanged by injury-induced insulin resistance." (PMID 33100956, 2020). "Moreover, TG-increasing alleles of GCKR variants rs1260326 and rs1260333 lowered insulin and HOMA-IR and reduced the risk of insulin resistance in Chinese." (PMID 31910446, 2020). "Prolonged fasting increases stress, combined with surgical trauma, leads to increased glucocorticoids and glucagon, reduces insulin sensitivity, and reduces utilization of glucose in peripheral tissues, ultimately leading to postoperative hyperglycemia and increased insulin resistance." (PMID 32219135, 2020). "Insulin resistance is likely a primary factor and general anesthesia per se may be contributory; a recent animal study reveals an increase in insulin resistance by almost 50% and insulin effects at the liver were almost completely suppressed." (PMID 31901245, 2020). "The primary metabolic defect seen in type II DM is insulin resistance, which is the inability of the peripheral tissue to respond to insulin and Β-cell dysfunction that occurs as inadequate insulin secretion in the presence of insulin resistance and hyperglycemia." (PMID 33200060, 2020). "Thus, while liver-specific aged L-Mttp−/− mice developed hepatic insulin resistance, this defect in hepatic insulin action was reversible by CRMP treatment." (PMID 32907986, 2020). "The measurement of daily insulin dose as a ratio per body weight may be a better indicator of insulin resistance than other biomarkers such as BMI, waist circumference of total daily insulin dose." (PMID 32344939, 2020). "Longer term and especially dose-response studies on mildly insulin resistant participants are required to establish the extent to which (poly)phenols and (poly)phenol-rich foods may improve insulin resistance in compromised groups." (PMID 33066504, 2020).
Insulin resistance (continued). "Available evidence shows that the direct β-cell damage, inflammation-induced insulin resistance, hypokalemia-related inhibition of insulin secretion by β-cells and corticosteroid use in the treatment of COVID-19 contribute to the poor glycemic control in patients with DM who develop COVID-19." (PMID 33297431, 2020). "Any defects in the insulin signaling pathways could potentially contribute to the development of insulin resistance and DM." (PMID 32215179, 2020). "The same group has also reported that high fat diet augmented the content and fractional synthesis rate (FSR) of diacylglycerol (DAG) and ceramides in the liver which was accompanied by systemic insulin resistance and inhibition of hepatic insulin signaling pathway under insulin stimulation." (PMID 33133018, 2020). "This paradox may be resolved if we assume that the inhibition of insulin secretion by β-cells may preserve these cells from becoming exhausted under continuous stimulation by high glucose and may also reduce insulin resistance." (PMID 32992875, 2020). "Additionally, the serum levels of WD-enhanced insulin and insulin resistance showed reduced trend by supplementation with BA." (PMID 33114130, 2020). "The cause is likely largely due to insulin secretion with little or no insulin resistance as suggested by many studies." (PMID 32399348, 2020). "Biochemical tests including lipid profile, fasting plasma glucose, insulin, glycosylated hemoglobin Type A1c (HbA1c), homeostatic model assessment of insulin resistance (HOMA-IR), blood pressure, and body composition were evaluated at baseline and at the 12th week in diet interviews." (PMID 33096684, 2020). "Type 1 diabetes (T1D) is characterized by insufficient insulin secretion due to complete destruction of the insulin-producing β-cells of the pancreas, while T2D more commonly results from insulin resistance, namely a reduced response to insulin by the target tissues." (PMID 32093016, 2020). "Evidence from our meta-analysis showed that vitamin D supplementation resulted in lowering blood fasting glucose levels in addition to improving insulin resistance, as seen by a significant decrease in serum fasting insulin and HOMA-IR along with a slight increase in QUICKI." (PMID 33424968, 2020). "In addition, anxiety and mental stress contribute to elevated cortisol concentrations which advance insulin resistance to hyperinsulinemia, and insulin promotes SNS activity." (PMID 32492920, 2020). "Type 2 diabetes is a multifactorial disease with impaired insulin secretion and insulin resistance." (PMID 32097444, 2020). "Regarding the molecular mechanism underlying the progression of sarcopenia in the SDT group, disruption to insulin/IGF-1-Akt signaling due to insulin resistance and low serum IGF-1 levels was considered to provoke abnormalities in muscle strength and mass in the SDT group." (PMID 32405506, 2020). "At the level of individual genes, shared features common to aging or insulin resistance and exercise have been, to date, underwhelming, and we also noted limited overlap between the HypAt-regulated genes and age- or insulin-sensitivity-regulated genes." (PMID 32755574, 2020). "In transgenic mice, global overexpression of the Se-dependent cytosolic glutathione peroxidase (GPx 1) leads to obesity and insulin resistance, whereas cell-type restricted overexpression in pancreatic beta cells specifically results in elevated insulin biosynthesis and secretion." (PMID 32905881, 2020). "Similarly, Treg depletion in 6‐week‐old diabetic leptin‐deficient db/db mice also increases fasting glucose levels, lowers insulin sensitivity and elevates homeostatic model assessment of insulin resistance, relative to untreated db/db mice." (PMID 32463116, 2020). "The lack of BCAA metabolic signature may suggest that ADT‐induced insulin resistance may occur through a distinct metabolism, such as the reduced ketone bodies and insulin response." (PMID 32232974, 2020).